IL4 (interleukin 4)
Diseases named in the same sentence as IL4 in open-access papers (continued):
Sharing a sentence is not in itself a finding about the gene and the disease.
airway hyperresponsiveness (continued). "At the physiological level, biologic therapies contribute to the reduction in type 2 inflammation by targeting specific cytokines (IL-4, IL-5, IL-13) and IgE, leading to decreased airway hyperresponsiveness, reduced mucus production, and improved lung function." (PMID 41302212, 2025). "IL-4 and IL-5 regulate the maturation and release of eosinophils in the bone marrow, while IL-13 promotes B cell differentiation and plays a leading role in airway inflammation, airway hyperresponsiveness, and mucus secretion." (PMID 40070820, 2025). "Activation of the IL-4/IL-13 pathway promotes profound airway hyperresponsiveness." (PMID 37214308, 2023). "Both IL-4 and -13 act as major mediators in the eosinophil accumulation and IgE synthesis via B cells; thus, they contribute the mucus production, bronchial fibrosis, and airway hyperresponsiveness symptoms." (PMID 37998734, 2023). "Our results showed that lonicerin significantly reduced airway hyperresponsiveness the number of inflammatory cells (especially eosinophils) and the elevation of interleukin (IL)-4, IL-5, IL-13 and eotaxin in bronchoalveolar lavage fluid (BALF) supernatants of mice." (PMID 36618942, 2022). "Indeed, IL-4 promotes both Th2 cell differentiation and biosynthesis of immunoglobulins E (IgE), whereas IL-13 is mostly responsible for airway hyperresponsiveness, mucus overproduction, and bronchial structural changes." (PMID 35350765, 2022). "In addition, it also induced eosinophilic inflammation, the production of IL-4, IL-5, IL-13, and IL-33 in bronchoalveolar lavage fluid, and airway hyperresponsiveness." (PMID 34079051, 2021). "Increased airway hyperresponsiveness after EC vapor inhalation.Increased infiltration of inflammatory cells, including eosinophils, into airways from blood.Stimulation of production of Th2 cytokines such as IL-4, IL-5 and IL-13 and allergen-specific IgE." (PMID 34442368, 2021). "Studies have reported that local administration of IL-4 gene plasmids prior to antigen challenge could stimulate the airway hyperresponsiveness and accumulation of eosinophils in mice." (PMID 33087044, 2020). "DK-1014 reduced the airway hyperresponsiveness, inflammatory cell counts and cytokine levels (IL-4, 5, 13) in bronchial alveolar lavage fluid (BALF) and immunoglobulin E in serum, and attenuated inflammatory cell infiltration and mucus hypersecretion in lung tissue." (PMID 30696844, 2019). "In addition, matrine inhibits ovalbumin-induced airway hyperresponsiveness, inflammatory cell infiltration, and goblet cell differentiation via regulating Il-4, IL-13, and TNF-α expression." (PMID 30800071, 2019). "On the contrary, in mice receiving intranasal exposure of high-dose HDM at early time points and multiple treatments of low-dose HDM at later time points, HRV triggers both type 1 and type 2 responses including IL-4 and IL-13 expression, eosinophilic inflammation and airway hyperresponsiveness." (PMID 30513770, 2018). "In the present study, we provide evidence that IL-33 exacerbates antigen-induced asthmatic responses, including airway hyperresponsiveness, inflammation and remodeling, mast cell activation, production of IgE and cytokines including IL-4, IL-5 and IL-13, and accumulation of pulmonary ILC2s." (PMID 28652606, 2017). "We previously found that, in OVA-sensitized and -challenged mice with allergic airway inflammation, RV infection increases eotaxin-1, IL-4 and IL-13 production from alternatively-activated (M2 polarized) airway macrophages, further enhancing eosinophilic inflammation and airways hyperresponsiveness." (PMID 24907978, 2014). "Treatment of mice with the C. elegans crude extract significantly decreased methacholine-induced airway hyperresponsiveness and the total cell counts and levels of IL-4, IL-5 and IL-13 in the bronchoalveolar lavage fluid but increased the levels of IFN-γ and IL-12." (PMID 22558152, 2012).
airway hyperresponsiveness (continued). "IL‐5 is essential for the recruitment and survival of eosinophils, while IL‐4 may contribute significantly to phenotypic or functional changes in asthma, such as airway hyperresponsiveness, eosinophil infiltration, and mucus overproduction, potentially exacerbating airway inflammation." (PMID 41159221, 2025). "Prebiotic intervention significantly reduced airway hyperresponsiveness (AHR) and type 2 cytokines (IL-4, IL-5, IL-13) and various cell counts, including neutrophil, macrophage, lymphocyte, eosinophil, and total bronchoalveolar (BALF)." (PMID 41754200, 2026). "Sphingosine kinase inhibitor reduced inflammatory cell infiltrates, IL‐4, IL‐5, and eotaxin levels in BAL fluid, and suppressed airway hyperresponsiveness." (PMID 38342758, 2024). "Most importantly, intratracheal instillation of shikonin can down-regulate the release of IL-4, IL-5, IL-13, and TNF-α in BALF and reduce pulmonary eosinophils and airway hyperresponsiveness." (PMID 39444792, 2024). "Then airway hyperresponsiveness (AHR), eosinophil percentage, levels of interleukin (IL)‐33, IL‐25, IL‐13, IL‐5, IL‐4, total and ovalbumin (OVA)‐specific immunoglobulin (Ig)E, and lung histopathology were evaluated." (PMID 38664220, 2024). "In HDM-sensitized mice, chloroquine attenuated airway hyperresponsiveness (AHR), inflammation and remodeling with an inhibition of immunoglobulin E, IL-4/-13, and TGF-β1 in BALF." (PMID 35721212, 2022). "Amox- and TMP/SMX-treated animals displayed more severe allergic airway inflammation parameters with increased airway hyperresponsiveness, reduced lung alveolar volume, and increased levels in BAL of IL-4 and IL-6." (PMID 35785028, 2022). "The results demonstrated that matrine alleviated eosinophil infiltration, airway hyperresponsiveness (AHR), and airway inflammation by inhibiting Th2 cytokines or the IL-4/IL-13/STAT-6 pathway in asthmatic mice." (PMID 33041782, 2020). "In Tlr9–/– mice, airway hyperresponsiveness (AHR) and the number of eosinophils decreased, and production of the Th2 cytokines IL-13, IL-5, and IL-4 was suppressed, compared with in wild-type mice." (PMID 33093516, 2020). "OVA-sensitized and challenged mice had significantly increased number of BALF inflammatory cell count, particularly eosinophil count, airway hyperresponsiveness, significantly elevated BALF levels of IL-4 and IL-5, and elevated BALF total and OVA-specific IgE." (PMID 32029879, 2020). "IL-4 was important in CD4+ lymphocyte differentiation and the production of IgE,while IL-13 drived airway hyperresponsiveness, mucus production, and subepithelial fibrosis." (PMID 31747880, 2019). "Following OVA sensitization, HRV infection triggers eosinophilic inflammation and airway hyperresponsiveness, along with increased expression of mucins (Muc5AC and Muc5B), eotaxin-1/CCL11, IL-4 and IL-13." (PMID 30513770, 2018). "IgG-treated animals exhibited attenuated allergen-induced production of IgE, IL-4, and IL-13, along with impaired OVA-induced goblet cell hyperplasia and Muc5ac expression and suppressed airway hyperresponsiveness, consistent with a shift away from a Th2 response." (PMID 40725026, 2025). "We observed a significant reduction of airway hyperresponsiveness (AHR), lung eosinophil and lymphocyte counts, serum IgE, Th2 cytokines (IL-4 and IL-13), goblet cell hyperplasia and mucus production in mice that had reduced GRK2 expression specifically in T cells." (PMID 35386975, 2021). "A delayed and prolonged type 2 immune response which is featured with increased expression of IL-4, IL-5 and IL-13, as well as mucous metaplasia and airways hyperresponsiveness occurs in HRV-infected immature but not in adult mice." (PMID 30513770, 2018). "Δ12-PGJ3 did not induce histamine and IL-4 in primary murine BMMCs, which is in agreement with reduced airways hyperresponsiveness in mice." (PMID 24312486, 2013).
airway hyperresponsiveness (continued). "Δ12-PGJ3 failed to increase histamine and IL-4 in BMMCs, which is in agreement with reduced airway hyperresponsiveness in mice." (PMID 24312486, 2013). "T helper type 2 immune responses such as high levels of IL-4 versus IFN-γ and the release of IL-5 and IL-13 cytokines are known to contribute to eosinophil recruitment to the lung, goblet cell formation from epithelial cells, mucus production and airway hyperresponsiveness." (PMID 25658239, 2015). "IFN-gamma also inhibits allergic responses through its capacity to inhibit IL-4 mediated effects but may also contribute to airway hyperresponsiveness especially in non-atopic subjects." (PMID 19781072, 2009). "IL-9 may be involved in IL-4-triggered IgE production in vitro, mast cells and eosinophils recruitment and activation to the lung, bronchial mucus cell hyperplasia (and MUC4 induction), subepithelial deposition of collagen, and airway hyperresponsiveness." (PMID 18315837, 2008). "Airway hyperresponsiveness as well as levels of IFN-γ, IL-13, IL-6, and IL-10 was lower in the lungs of asthmatic March1−/− mice compared to WT, whereas lung levels of TNF-α, IL-4, and IL-5 were not significantly different." (PMID 29854835, 2018).
diabetes (121 papers, 2007 to 2026). "IL-4 circulating levels are decreased in elderly people and low levels of IL-13 are associated with increased mortality risk in diabetes." (PMID 39193712, 2025). "Strikingly, the effect of IL-4 on T cell selection translates into clonal deletion of T cells specific for β cell associated Ag and resistance to the development of diabetes." (PMID 39621313, 2024). "The results of the analysis revealed that two serum cytokines (IL‐4 and IL‐17), three clinical risk factors (gender, smoking, and diabetes), and HDL‐C were independently associated with CAD after controlling for age, gender, and other related factors." (PMID 38146141, 2023). "In our study, we found that the induction of diabetes was associated with decreased levels of IL-2, IL-7, and IL-4, which reflects perturbations in adaptive immunity." (PMID 35554836, 2022). "STZ-induced diabetes was associated with increased levels of blood glucose, ROS, and IL-6 and decreased levels of IL-2, IL-7, IL-4, and GSH." (PMID 35554836, 2022). "The STZ-induced mice that were treated with combined bacterial strains carrying plasmids encoding IL-4 and IL-10 showed lower incidence of diabetes and more preserved pancreatic islets than the mice that received the individual bacterial strains." (PMID 33604389, 2021). "Several studies have reported that the interactions of the IL-4 and IL-4R genotypes are associated with diabetes, cancer, and pemphigus foliaceus in humans." (PMID 33920608, 2021). "A decreased IL-4 level was also found in patients with T2DM with RA compared to that in the control group, indicating that not only diabetes but also RA characterized by eGFR <60 mL/min/1.73 m2 is associated with decreased IL-4 level." (PMID 32130282, 2020). "The results of this research suggest that upregulation of cerebral COX-2 gene along with the decrease in cerebral IL-4 and enhanced cerebral apoptosis is critically involved in cerebral damage associated with diabetes and cerebral ischemic-reperfusion." (PMID 25191525, 2014). "Vascular calcifications were independently associated with increased all-cause mortality in RA patients.IL-4 and anti-citrullinated ApoE levels were significantly elevated in patients with vascular calcifications.Prednisone use and diabetes were positively associated with vascular calcifications." (PMID 41179568, 2025). "Additionally, it has been established that the induction of diabetes in animal models is associated with perturbations in the levels of different cytokines, including IL-2, IL-7, and IL-4, which can perturb adaptive immunity." (PMID 35554836, 2022). "In fact, several studies have also reported the regulatory roles of T-helper cell cytokines in multiple low doses of streptozotocin (MLD-STZ) diabetes model, suggesting the pathogenic role of IL-17 and IL-1β and protective role of IL-6, IL-10, and IL-4 in MLD-STZ mice." (PMID 29317893, 2017). "Previously, we have shown that TSA treatment alleviated T1D in NOD mice and also up-regulated the expression of the transcription factor Tbx21/Tbet and Ifng genes without altering the levels of some of the genes implicated in diabetes such as Il4, Il17, Il18, and Tnfa in activated T lymphocytes." (PMID 23383062, 2013). "The immune factors associated with triggering diabetes, including the cytokines of IFN-γ and IL-4, the Thl/Th2 polarization key transcription factors T-bet and GATA-3 were determined and analyzed." (PMID 39847549, 2025). "In contrast, the anti-inflammatory cytokine IL-4 was downregulated, possibly attributing to chronic inflammation in diabetes." (PMID 40362271, 2025). "In patients with diabetes, IL-4 levels have been shown to be higher than in patients in a control group." (PMID 40672460, 2025). "The nanofibrous heparin-modified gelatin microsphere can improve IL-4 stabilization and prolong IL-4 release to modulate macrophage polarization from M1 to M2 phenotype, promoting bone regeneration in diabetes mellitus." (PMID 39258053, 2024).
diabetes (continued). "Conversely, age inversely affected IL-4 levels, and diabetes mellitus negatively influenced IL-6 levels." (PMID 39456722, 2024). "Subgroup A1 had significantly higher levels of IL-35 and IL-4, as well as IL-12, and had a significantly shorter diabetes duration than subgroup A2." (PMID 38542165, 2024). "Our data demonstrated that the serum proinflammatory cytokines IL-1β, TNF-α, IL-2, IFN-γ, and IL-4 and the anti-inflammatory cytokine IL-10 were dysregulated in diabetes and improved by OI intervention." (PMID 36918798, 2023). "Multivariate logistic regression analysis indicated that two serum cytokines (IL‐4 and IL‐17), one protective factor (high‐density lipoprotein cholesterol [HDL‐C]), and three risk factors (sex, smoking, and diabetes) were independently predictive of CAD." (PMID 38146141, 2023). "Along the same line, findings from in vitro studies indicated that chronic activation of macrophages and innate immunity via IL-4 can result in impaired defense against abdominal obesity and diabetes." (PMID 36501156, 2022). "Type 2 T helper (Th2) cells produce IL-4, IL-5 and IL-10 and are protective against T1D, since the expression of IL-4 ameliorates diabetes in NOD mice." (PMID 36091068, 2022). "The existing biological pathways include: The “immune system” unfolds pathways involving interleukin-4, 10, and 13 which are involved in the pathology of a wide variety of age-related diseases such as cardiovascular diseases, diabetes and cancers." (PMID 36437990, 2022). "There was an increase in IL-4 levels in the diabetes groups compared to the control groups, and the increase in the D+2D-CM (p < 0.01) and D+3D-CM (p < 0.05) groups were statistically significant compared to the C group." (PMID 36451229, 2022). "The high-glucose environment of diabetes significantly increases the cytokines, such as interleukin 4(IL-4), interleukin 5(IL-5), interleukin 6(IL-6), interleukin 13(IL-13), and tumor necrosis factorα (TNF-α)." (PMID 35669482, 2022). "Approaches favoring Th2 activity and administration of cytokines that downregulate Th1 activities, such as IL-4 and IL-10, have shown success in suppress insulitis and prevent diabetes." (PMID 33604389, 2021). "Later, they also reported tolDCs transduced for IL-4 expression to prevent diabetes in NOD mice when applied i.v." (PMID 31139178, 2019). "Tolerogenic DCs propagated with GM-CSF+IL-4 from BMDCs isolated from GM-CSF-treated NOD mice also decreased development of diabetes when applied to 3-week-old NOD recipient mice." (PMID 31139178, 2019). "GM-CSF + IL-4 generated DCs transduced with IL-4 were able to prevent diabetes in NOD mice with advanced insulitis." (PMID 29503651, 2018). "Our diabetes-preventive unloaded tolDCs were prepared in the presence of GM-CSF + IL-4, further treated with dexamethasone and vitamin D2 and stabilized by a final activation with MPLA." (PMID 29503651, 2018). "Such protection is dependent on the IL-4 production by iNKT cells, and activation of iNKT cells to produce IL-4 by cognate lipid antigen α-Galcer prevents diabetes in NOD mice." (PMID 29997620, 2018). "Zipris used retro­viral construction of IL-4 gene for the prevention of auto­immune diabetes, however there were still previous defects as mentioned about Kapturczak report." (PMID 23843817, 2012). "Treatment with IL-4 has been shown to maintain Th2 CD4+ T cell responses that inhibit the progression of diabetes." (PMID 20686610, 2010). "Our data are consistent with the finding that high levels of IL-4 secretion are required by the transduced DC in order for a delay in diabetes onset to be seen." (PMID 20686610, 2010). "Similar to previous results, we demonstrate the ability of IL-4 overexpressing DC to prevent diabetes onset in the NOD model." (PMID 20686610, 2010). "Our results are consistent with a recent report demonstrating that transduction of DC with a lentiviral vector expressing IL-4 prevents the onset of diabetes in 12-week old NOD mice." (PMID 20686610, 2010).